SMAD4 (SMAD family member 4)
Diseases named in the same sentence as SMAD4 in open-access papers (continued):
Sharing a sentence is not in itself a finding about the gene and the disease.
Myhre syndrome (33 papers, 2016 to 2025). "Myhre syndrome is caused by recurrent missense variants in SMAD4, which causes dysregulation of TGFβ signalling." (PMID 41290615, 2025). "Patients with Myhre syndrome—another monogenic disorder—harbor SMAD4 mutations and exhibit skin lesions, vascular calcification, and cardiovascular abnormalities." (PMID 40740820, 2025). "We show that Myhre syndrome-causing mutations in SMAD4, a gene operating outside the canonical RAS-MAPK signaling pathway, are positively selected in the male germline." (PMID 39116879, 2024). "In humans, the rare autosomal disorder Myhre syndrome is caused by a gain-of-function mutation in SMAD4, which is associated with hearing loss among other musculoskeletal anomalies, as well as reports of unilateral VS." (PMID 37885485, 2023). "On the other hand, gain of function mutations in SMAD4 have been associated with a different clinical presentation, a complex connective tissue disorder known as Myhre syndrome." (PMID 35685436, 2022). "Myhre syndrome (MS) is a rare genetic disease characterized by skeletal disorders, facial features and joint limitation, caused by a gain of function mutation in SMAD4 gene." (PMID 35907855, 2022). "The restrictive pattern of SMAD4 mutation is the cause of the genetic homogeneity of Myhre syndrome, which is reflected in the clinical homogeneity." (PMID 34236823, 2021). "The preterm baby was finally diagnosed with Myhre Syndrome by clinical phenotypes and mutation of SMAD4 gene." (PMID 34236823, 2021). "Mutations in the SMAD4 gene are associated with four different phenotypes, one of which is Myhre syndrome, which involves microcephaly, intellectual disability, and laryngeal/trachea stenosis, dysmorphia, and arthropathy." (PMID 33921653, 2021). "The mutation of SMAD4 gene can cause four different diseases, i.e., juvenile polyposis syndrome, hereditary hemorrhagic telangiectasia syndrome, Myhre syndrome, and pancreatic cancers, reflecting different clinical phenotypes caused by the same gene variation." (PMID 34236823, 2021). "Myhre syndrome is a rare condition caused by a mutation in the SMAD4 gene, which leads to a defective TGF-β/BMP signaling, resulting in the proliferation of abnormal fibrous tissues." (PMID 32175297, 2020). "Cardiovascular abnormalities of Myhre syndrome were related to the capability of the SMAD4 encoded protein to harmonize various signaling pathways." (PMID 33224271, 2020). "Myhre syndrome is a genetic disorder caused by gain of function mutations in the SMAD Family Member 4 (SMAD4) gene, resulting in progressive, proliferative skin and organ fibrosis." (PMID 32917212, 2020). "Myhre syndrome is caused by mutations in SMAD encoding for SMAD4 protein, a transducer mediating transforming growth factor β (TGF-β) signalling." (PMID 32917212, 2020). "Further, in humans, SMAD4 gain of function mutations cause Myhre syndrome, which includes CHD as a common (~2/3rds of patients) phenotypic finding." (PMID 31314787, 2019). "Smad4 is an intracellular effector of the TGFβ family that has been implicated in Myhre syndrome, a skeletal dysplasia characterized by short stature, brachydactyly and stiff joints." (PMID 28167493, 2017). "Mutations at a single codon in Mad homology 2 domain of SMAD4 can cause Myhre syndrome, which is a developmental disorder characterized by a shortness in stature, hands, feet, and so on." (PMID 27113217, 2016). "Here, we demonstrate the selfish nature of the SMAD4 DNMs causing Myhre syndrome (MYHRS)." (PMID 39116879, 2024). "Myhre syndrome is a rare disorder caused by a heterozygous mutation in the SMAD4 gene." (PMID 34395338, 2021).
Myhre syndrome (continued). "Gain of function mutations in SMAD4 in humans cause Myhre Syndrome with cardiomyopathy." (PMID 34488850, 2021). "SMAD4 is located in 18q21.2, and its gene mutation is the cause of Myhre syndrome." (PMID 34236823, 2021). "Furthermore, SMAD4 mutations have been identified in patients with Myhre syndrome, which features cryptorchidism." (PMID 29197384, 2017). "However, the Myhre syndrome caused by SMAD4 mutation has its own characteristics." (PMID 34236823, 2021). "Moreover, we previously found that inclusions are also present in fibroblasts of GPHYSD patients carrying FBN1 mutations and Myhre syndrome (MIM139210) patients carrying SMAD4 mutations, suggesting that a common pathway is responsible for the formation of such inclusions." (PMID 31516831, 2019). "The defects we observed in Smad4-deficient chondrocyte proliferation, size, orientation, and shape, coupled with abnormal proteoglycan content, could contribute to the pathology of Myhre syndrome, most notably the joint stiffness, bracydactyly, restricted thoracic development, and short stature." (PMID 28167493, 2017). "However, the cellular basis of physeal defects in Smad4-deficient mice and skeletal deformities in Myhre syndrome remains unclear." (PMID 28167493, 2017). "Skin fibroblasts from patients with Myhre syndrome show increased SMAD4 expression, impaired matrix deposition, and altered expression of genes encoding matrix metalloproteinases and related inhibitors." (PMID 32917212, 2020). "In one such example, dysregulation of Smad4, a common intracellular effector of all transforming growth factor β (TGFβ) family members, is responsible for human Myhre syndrome and characterized by short stature, brachydactyly, and joint stiffness." (PMID 28167493, 2017). "Dominant negative variants of SMAD4 are not known to be associated with cancer but have been reported in Myhre syndrome (a congenital connective tissue disorder)." (PMID 40004106, 2025). "Myhre syndrome (SMAD4 gene defect) is characterized by short stature, small hands, thick skin, mental retardation, microcephaly, midface hypoplasia, prognathism, blepharophimosis, square body shape, broad ribs, iliac hypoplasia, flattened vertebrae, thick calvaria, and congenital heart defects." (PMID 39421111, 2024). "Besides JPS and GI cancers, BMPR1A is also associated with HMPS, polyposis, superior coloboma, and CHD, while SMAD4 is also associated with HHT, Myhre syndrome, Loeys-Dietz syndrome, cholangiocarcinoma, and thoracic aortic aneurysms and aortic dissections." (PMID 33327285, 2020). "Smad4 dysregulation results in skeletal dysplasias, such as Myhre syndrome." (PMID 28167493, 2017). "Myhre syndrome is a skeletal dysplasia characterized by short stature, brachydactyly, and joint stiffness, with laryngotracheal stenosis and restrictive respiratory insufficiency leading to increased mortality as the result of Smad4 dysregulation." (PMID 28167493, 2017).
glioma (29 papers, 2010 to 2025). A benign or malignant brain and spinal cord tumor that arises from glial cells (astrocytes, oligodendrocytes, ependymal cells). "In the present study, glioma-associated microglia expressed SMAD4 in human glioblastoma tumors in vivo and microglia exposed to GCM showed increased expression of SMAD4 in vitro." (PMID 29861845, 2018). "In this regard, this study shows robust expression of SMAD4 in glioblastoma tumors and in glioma-associated microglia." (PMID 29861845, 2018). "This study further established that miR-146a suppresses tumorigenic gene, MMP9 in glioma-associated microglia and glioma cell viability through its target SMAD4." (PMID 29861845, 2018). "We further confirmed that the loss of SMAD4 was a significant and independent prognostic indicator in glioma by multivariate analysis." (PMID 21791112, 2011). "By multivariate analysis, the loss of SMAD4 expression was a significant and independent prognostic indicator for patients with glioma besides age, WHO grade and KPS." (PMID 21791112, 2011). "The analysis showed that miRNAs downregulated both by the hotspot and deleterious SMAD4 mutations are associated (adjusted P < 0.01) with similar cancer-related processes, including ‘Pathways in cancer’, ‘ErbB signaling pathway’, ‘Glioma’, and ‘Proteoglycans in cancer’." (PMID 33406242, 2021). "Overall, these results indicate that the possible interaction between SMAD4 and NF-κB in glioma-associated microglia may determine the tumor progression." (PMID 29861845, 2018). "Downregulation of miR-146a in glioma-associated microglia as observed in the present study may favour tumorigenesis through increased expression of SMAD4 and its downstream genes which are involved in tumor progression." (PMID 29861845, 2018). "This suggests that miR-146a regulates SMAD4 expression in glioma-associated microglia." (PMID 29861845, 2018). "Moreover, the role of SMAD4 in microglial functions in gliomas has been poorly understood and hence, this study is aimed to understand the role of SMAD4 in tumor-associated microglia in mediating tumor progression." (PMID 29861845, 2018). "Moreover, this study demonstrates that glioma-associated microglia promote tumorigenesis through SMAD4 expression, since glioma cells treated with conditioned medium derived from shSMAD4 microglial cells showed decreased viability." (PMID 29861845, 2018). "elucidated the role of miR‐146a‐5p in glioma by targeting SMAD4 to suppress the tumorigenic gene MM9, thereby impeding glioma growth and progression." (PMID 40785027, 2025). "These cells are driven by transcription factors such as SMAD4 to release IL‐12 or nCD47‐SLAMF7 fusion proteins for glioma cell therapy." (PMID 39713206, 2024). "It is reported that increased Smad4 drives the invasion pathways of glioma, and the level of Smad4 is lower in the dorsolateral prefrontal cortex and anterior cingulate cortex from individuals with schizophrenia compared with that in the control group." (PMID 37192007, 2023). "Sodium valproate inhibits glioma invasion and metastasis through the regulation of Smad4 expression." (PMID 35251569, 2022). "The protein levels of TGF-β1, TGF-β2, Smad4, and p-Smad2 in the siRNA1 and siRNA2 groups were significantly downregulated compared to the siNC group in U87 glioma cells." (PMID 35571491, 2022). "In our study, low expression of Smad4 in glioma cells produced a similar effect to that of VPA, with inhibition of tumor invasion and metastasis." (PMID 35251569, 2022). "According to the gray value calculation, the downregulation of TGF-β1, TGF-β2, Smad4, and p-Smad2 protein levels in the siRNA1 and siRNA2 groups was statistically significant compared to controls in U87 glioma cells (p < 0.05)." (PMID 35571491, 2022). "U87 glioma cells were transfected with Smad4 plasmid and small interfering RNA, and the changes of EMT-related protein indexes in U87 cells after up- or downregulation of Smad4 were detected by Western blotting." (PMID 35251569, 2022).
glioma (continued). "This miR decreased epidermal growth factor receptor (EGFR) and NF-κB protein in 9L glioma cells in vitro, and inhibited small mothers against decapentaplegic (SMAD)-4, a protein of the SMAD family whose loss indicates poor outcome in glioma." (PMID 32349317, 2020). "Our analyses on SMAD4 in glioma revealed a likely tumor-suppressive role of the gene, which is corroborated by another study demonstrating reduced SMAD4 expression during glioma tumor progression." (PMID 32807122, 2020). "SMAD4 has been shown to be a direct target of miR-146a, which was repressed in microglia treated with glioma-conditioned medium." (PMID 31133802, 2019). "The enhanced SUMOylation of Smad4 is critical for DNA damage-induced activation of in-resistant glioma cells." (PMID 31345225, 2019). "Taken together, the present study suggests that microglial SMAD4 which is epigenetically regulated by miR-146a promotes microglial migration in gliomas and glioma cell viability." (PMID 29861845, 2018). "Further, knockdown of SMAD4 in microglia decreased the migration of microglial cells towards GCM, indicating that SMAD4 promotes microglial migration in glioma environment." (PMID 29861845, 2018). "As SMAD2/3 forms a complex with SMAD4 to regulate TGFβ responsive genes, the effect of glioma microenvironment on SMAD4 expression in microglia was determined by western blot and immunocytochemistry." (PMID 29861845, 2018). "The results indicate that there is a decrease in viability of glioma cells when treated with medium from SMAD4 knockdown microglial cells, suggesting that suppression of SMAD4 in microglia decreases the viability of glioma cells." (PMID 29861845, 2018). "In order to delineate the epigenetic mechanisms that regulate SMAD4 expression in glioma-associated microglia, we examined the 3’UTR of the Smad4 mRNA sequence to identify miRNA binding sites." (PMID 29861845, 2018). "In this study, SMAD4, a mediator of the TGFβ signaling pathway was upregulated in microglia exposed to glioma conditioned medium and was found to be robustly expressed in microglia associated with human glioblastoma tissues." (PMID 29861845, 2018). "In order to determine the effect of knockdown of SMAD4 in microglia on glioma cell viability, glioma cells were treated with conditioned medium derived from shSMAD4 microglial cells." (PMID 29861845, 2018). "It has also been demonstrated that SMAD4 which was found to be post-transcriptionally regulated by miR-146a, regulates the migration of microglial cells in response to glioma conditioned medium." (PMID 29861845, 2018). "Further in vivo studies are required to evaluate the therapeutic effect of miR-146a and SMAD4 on glioma growth and progression." (PMID 29861845, 2018). "Overall, the present study implicates the role of miR-146a-SMAD4 in regulating microglial functions in glioma tumors." (PMID 29861845, 2018). "We also found a significant decrease of SMAD4 expression in glioma compared with normal brain tissues (P < 0.001)." (PMID 21791112, 2011). "As the results of Western blot analysis, we found that SMAD4 protein expression tended to increase from the glioma to the normal tissue." (PMID 21791112, 2011). "In conclusion, our data provides convincing evidence for the first time that the reduced expression of SMAD4 at gene and protein levels is correlated with poor outcome in patients with glioma." (PMID 21791112, 2011). "There was a significant positive correlation between the expression of SMAD4 mRNA and protein expression levels from the same glioma tissues (rs = 0.886, P < 0.001)." (PMID 21791112, 2011). "Next, we analyzed the relationship between SMAD4 expression and the glioma stage as well as the survival of patients." (PMID 21791112, 2011). "There was a conspicuous decrease in the expression of SMAD4 mRNA from the control brain tissues to glioma tissues (P < 0.001)." (PMID 21791112, 2011).
glioma (continued). "SMAD4 mRNA and protein levels were both lower in glioma compared to control on real-time PCR and Western blot analysis (both P < 0.001)." (PMID 21791112, 2011). "Our data provides convincing evidence for the first time that the reduced expression of SMAD4 at gene and protein levels is correlated with poor outcome in patients with glioma." (PMID 21791112, 2011). "In the current study, we investigated the expression of SMAD4 in 252 cases of human glioma and compared the expression with tumor grade and survival rates of patients." (PMID 21791112, 2011). "SMAD4 expression was studied in a total of 252 glioma specimens of which 113 were low grade glioma (grade I and II) and 139 were high grade (grade III and IV)." (PMID 21791112, 2011). "Kaplan-Meier analysis of the survival curves showed a significantly worse overall survival for patients whose tumors had low SMAD4 levels, indicating that low SMAD4 protein level is a marker of poor prognosis for patients with glioma." (PMID 21791112, 2011). "Moreover, glioma cell proliferation was reduced when treated with conditioned medium from SMAD4 downregulated or miR-146a up-regulated microglia." (PMID 31133802, 2019). "Given the important role of miR-146a in microglia activation and gliomagenesis and its putative effect on SMAD4, this study attempted to understand the role of miR-146a and its putative target SMAD4 in microglia functions in tumor progression in glioma environment." (PMID 29861845, 2018). "In an in vitro cell line-based model increased protein levels of pSMAD2/3, total SMAD2/3 and SMAD4 were observed in murine BV2 microglia cultured in glioma conditioned medium (GCM), indicative of the activated TGFβ signaling pathway in microglia associated with glioma environment." (PMID 29861845, 2018). "In addition, miR-146a which was predicted to target SMAD4, was downregulated in microglia exposed to glioma conditioned medium treatment and regulated the expression levels of tumor supportive gene MMP9 in microglia." (PMID 29861845, 2018). "On the other hand, the cell viability assay revealed decreased viability of glioma cells when they were treated with conditioned medium derived from SMAD4 knockdown microglia or miR-146a overexpressed microglia as compared to glioma cells treated with the medium from control microglial cells." (PMID 29861845, 2018). "This decreased viability of glioma cells is also possible via SMAD4-induced negative regulation of NF-κB pathway in microglia, since recent studies have shown that SMAD4 knockdown in microglia induced pro-inflammatory cytokine, IL-6 in an NF-κB dependent manner." (PMID 29861845, 2018). "Immunohistochemistry showed that SMAD4 expression was decreased in glioma." (PMID 21791112, 2011). "However, little is known about the expression level of SMAD4 or its prognostic significance in human gliomas." (PMID 21791112, 2011). "Our data indicated that nearly 55% of glioma cases showed positive staining for SMAD4." (PMID 21791112, 2011). "SMAD4 may play an inhibitive role during the development of glioma and may be a potential prognosis predictor of glioma." (PMID 21791112, 2011). "SMAD4 mRNA expression was also reduced in glioma compared with control normal brain tissue." (PMID 21791112, 2011). "Our data demonstrated that SMAD4 protein was decreased in glioma compared to normal brain tissue." (PMID 21791112, 2011). "Besides, STC1 could affect the metastasis of glioma through the TGF-β/SMAD4 pathway, and affect the metastasis of liver cancer through the JNK pathway." (PMID 33644060, 2021). "SMAD4 may have an important role during the genesis or progression of glioma." (PMID 21791112, 2011). "In order to gain further insight into the status of SMAD4 in the progression of glioma, we used immunochemistry assay, quantitative real-time PCR and Western blot analysis to investigate the expression pattern of SMAD4 in glioma specimens and normal control brain tissues." (PMID 21791112, 2011).